LEP (leptin)
Diseases named in the same sentence as LEP in open-access papers (continued):
Sharing a sentence is not in itself a finding about the gene and the disease.
overnutrition (57 papers, 2009 to 2025). An imbalanced nutritional status resulting from excessive intake of nutrients. "In this study, we investigated the effects of overnutrition caused by lard and beef tallow intake on hypothalamic leptin responsiveness and energy balance." (PMID 40690443, 2025). "Overnutrition is associated with reduced sensitivity to metabolic hormones such as leptin in the hypothalamus." (PMID 40690443, 2025). "Maternal overnutrition has been linked to increased plasma leptin levels and adverse effects on offspring, whereas choline, an essential nutrient for foetal development, has shown promise in mitigating some negative impacts of maternal obesity." (PMID 38762543, 2024). "The dox-augmented leptin surge mimicked the greater leptin surge associated with overnutrition (small litter or maternal HFD) observed in the current study." (PMID 34475504, 2022). "Among the various proposed mechanisms, a growing body of evidence supports the view that leptin resistance, which is mainly induced by overnutrition, is intricately linked to a spectrum of cellular stress responses, including ER stress, oxidative stress, and chronic inflammation." (PMID 39916981, 2024). "Animal studies showed that overnutrition could cause insulin and leptin resistance in the hypothalamus via various pathways (e.g., oxidative stress, neurodegeneration and the activation of hypothalamic IKK beta/NF-kappa B paths)." (PMID 35736455, 2022). "As insulin signaling in the brain influences feeding behavior, SH‐BC‐893 may also enhance satiety by overcoming central insulin and leptin resistance stemming from the ER stress and inflammation associated with overnutrition." (PMID 34231322, 2021). "In addition, maternal obesity and maternal overnutrition are associated with Leptin hypermethylation and peroxisome proliferator-activated receptor (PPAR)α hypomethylation in the tissue of offspring’s oocytes and liver." (PMID 34828259, 2021). "Chronic overnutrition and neuroinflammation exacerbate these impairments, promoting hypothalamic leptin and insulin resistance, hallmarks of metabolic disease and contributors to cognitive decline." (PMID 41409607, 2025). "In the present study, we confirmed that male offspring of mothers exposed to undernutrition or overnutrition during pregnancy, in particular, had different plasma triglyceride and leptin levels." (PMID 40605344, 2025). "Modulation of offspring post-natal leptin levels by maternal obesity and/or postnatal overnutrition can impact the proper wiring of the feeding circuits." (PMID 41244059, 2025). "In sheep, the leptin surge is eliminated with maternal overnutrition and an elevated dam body condition score (BCS), but this has not been assessed in dairy cattle." (PMID 37233672, 2023). "In the context of maternal obesity and overnutrition, metabolic profiles shift more erratically, exposing developing offspring to increased levels of glucose, insulin, leptin, and BCAA leading to altered placental energy transfer." (PMID 35118010, 2021). "IKKβ/NF-KB is a master switch and central regulator of innate immunity that essentially connects overnutrition with compromised leptin signaling in the hypothalamus." (PMID 33741533, 2021). "A similar increase in circulating leptin levels and a reduction in arcuate leptin sensitivity has been reported in rat neonates exposed to chronic postnatal overnutrition." (PMID 32163401, 2020). "The decreased leptin sensitivity in the hypothalamic arcuate nucleus induced by early overnutrition is related to decreased expression of leptin receptor (LRb)." (PMID 32596284, 2020). "Altogether, our results identify GIPR/Rap1 signaling in the brain as a molecular pathway linking overnutrition to the control of neural leptin actions." (PMID 31403469, 2019). "Chemical chaperones, common compounds used for the reduction of ER stress, have the potential to improve leptin resistance in overnutrition and overweight conditions." (PMID 30018241, 2018).
overnutrition (continued). "Fat mass was increased significantly by both pre and postnatal overnutrition and leptin was higher in pups from obese mothers (HN and HS)." (PMID 21980407, 2011). "In addition to its effect on energy balance, lard intake resulted in better hypothalamic leptin responsiveness than beef tallow intake during overnutrition." (PMID 40690443, 2025). "Indeed, postnatal overnutrition has been shown to affect neuronal projections and synaptic transmission in females, due to an increase in excitatory transmission and lower leptin levels." (PMID 37630771, 2023). "Postnatal overnutrition affects leptin secretion and sensitivity, but whether postnatal overnutrition produces changes in the development of the synaptic transmission to ARH neurons is currently unknown." (PMID 32823489, 2020). "Although the complete absence of leptin signaling is rarely found in humans, both undernutrition and overnutrition are able to produce significant changes in leptin concentrations, leptin sensitivity or in the development of neurocircuits that regulate energy homeostasis." (PMID 33419354, 2020). "Plasma leptin levels are positively correlated with the number of Iba1-positive cells in the ARC of mice fed with a high saturated fat diet, raising the possibility that overnutrition-dependent inflammation is associated with leptin signaling in microglia." (PMID 31447640, 2019). "Overnutrition has been reported to activate hypothalamic IKKβ/NF-κB through endoplasmic reticulum stress in the hypothalamus region, which leads to the interrupted insulin and leptin signaling." (PMID 29025435, 2017). "This pathway has not been examined previously in AGRP neurons; instead, based on whole hypothalamus analysis, UPR has been primarily associated with overnutrition states and leptin resistance, as opposed to the energy-deficit condition examined here." (PMID 26329458, 2015). "As alterations in hypothalamic signaling induced by overnutrition (particularly hypothalamic leptin resistance) has been demonstrated to alter sympathetic outflow, this mechanism could also help couple sympathetic activation with systemic IR." (PMID 25358444, 2014). "This indicates that leptin may contribute to eliciting these metabolic changes in an adaptive response to overnutrition." (PMID 19727392, 2009). "Besides them, some authors observed alternations of serum leptin concentration due to overnutrition or undernutrition in the perinatal period, which may determine metabolic changes during childhood as well as adulthood." (PMID 40152811, 2025). "However, it cannot be excluded that leptin resistance induced by overnutrition may be related to saturated transport of blood-brain barrier and abnormal postsignal transduction mechanism." (PMID 32596284, 2020). "Considering that postnatal overnutrition induces anticipation of sexual maturation, as displayed by individuals that exhibit higher serum leptin levels at prepubertal stage, GABAB differential expression due to postnatal overnutrition may account for early sexual maturation." (PMID 32823489, 2020). "Hence, the aim of the study presented here was to analyze whether early overnutrition affects hypothalamic leptin sensitivity in peripubertal male rats." (PMID 29706935, 2018). "The observed suppression of the endogenous lipogenic program in the adipose tissue and liver most likely represents an important feature of the early adaptive responses to the state of overnutrition, whereby increased leptin levels may exert important regulatory actions." (PMID 19727392, 2009). "Therefore, it is likely that leptin may act upon the peripheral lipogenic program in the face of overnutrition to mediate body's metabolic adaptation responses." (PMID 19727392, 2009). "Besides, we noticed that the circulating leptin was increased for the control PBS and JMY31 (JMB84) treatments, which was supposed due to the potential overnutrition of “NC die” that we used." (PMID 35774455, 2022).
overnutrition (continued). "The NSAPP oxide transport chain is required for full activation of canonical leptin signaling in neurons but fails to function normally in states of overnutrition." (PMID 29632515, 2018). "In conclusion, the advancement in pubertal onset in males with neonatal overnutrition does not appear to be related to overt modifications in the central response to exogenous leptin during the peripubertal period." (PMID 29706935, 2018). "Overnutrition, especially in the form of HFD feeding, was shown to activate TLR4 signaling and downstream IKKβ/NF-κB pathway, leading to metabolic derangements such as central leptin resistance, systemic glucose intolerance, and weight gain." (PMID 22328600, 2012). "Therefore, a lack of leptin release or impaired leptin signalling leads to overnutrition, energy expenditure (EE) reduction and the development of an obesogenic phenotype and other chronic diseases." (PMID 34208585, 2021). "Although the complete absence of leptin signaling is rarely found in humans, both undernutrition and overnutrition are able to produce significant changes in serum leptin concentrations, leptin sensitivity or in the development of neurocircuits that regulate energy homeostasis." (PMID 30694175, 2019). "We also discuss a new explanation that is based on our group’s recent discovery of a signaling pathway—the NSAPP oxide transport chain—that is required for full activation of canonical leptin signaling in neurons but fails to function normally in states of overnutrition." (PMID 29632515, 2018). "Circulating leptin levels are increased as early as 10 days of life in both males and females with neonatal overnutrition and here we found that they continued to be higher at PND35 in males with neonatal overnutrition, as previously reported for peripubertal (PND30) females." (PMID 29706935, 2018). "For instance, leptin, an adipokine derived from adipose tissue, acts as an afferent input to the hypothalamic neurons with the negative feedback system, and long-term exposure to overnutrition gives rise to the resistance to leptin function despite high levels of circulating leptin." (PMID 29362519, 2017).
chronic kidney disease (56 papers, 2007 to 2025). Impairment of the renal function secondary to chronic kidney damage persisting for three or more months. "This positive effect on bones is supported by research showing that leptin is associated with reduced bone turnover and improved bone mineral density in patients with end-stage renal disease." (PMID 39062887, 2024). "Chronic kidney disease (CKD) is associated with an increased level of leptin and an abnormal fatty acid (FA) profile in the serum." (PMID 32182671, 2020). "Studies have reported that leptin is inversely related to glomerular filtration rate and positively associated with chronic kidney disease." (PMID 32130282, 2020). "Mills and colleagues reported that leptin and resistin are significantly associated with the risk and severity of chronic kidney disease." (PMID 32130282, 2020). "The results of some studies consistent with relatively high leptin levels caused weight loss in patients with end stage renal disease." (PMID 27689105, 2016). "High leptin levels associated with high adipose tissue mass may favor hypogonadism in the general population and chronic renal failure." (PMID 39062887, 2024). "However, few human studies have examined the putative association between plasma leptin levels and chronic kidney disease (CKD) in humans." (PMID 22666590, 2012). "The association between the adiponectin‐to‐leptin ratio (A/L ratio) and the risk of incident chronic kidney disease (CKD) is poorly understood." (PMID 38632706, 2024). "On Cox multivariate analyses ghrelin (HR 1.02; 95% CI 1.01 – 1.03; p < 0.0001) and leptin (HR 0.94; 95% CI 0.92 – 0.96; p < 0.0001) were significant predictors of death even after correction for other known risk factors such as presence of metastasis and chronic kidney disease." (PMID 25400234, 2014). "Leptin, anadipocyte-derived hormone, is also believed to play arole in many inflammation-related diseases, includingcardiovascular and chronic kidney diseases." (PMID 39139165, 2024). "Chronic kidney disease (CKD) causes specific hormonal disturbances, such as variations in leptin and testosterone levels and function." (PMID 39062887, 2024). "For example, hyperleptinemia is observed in subjects with chronic kidney disease and leptin levels increase with its progression." (PMID 37238651, 2023). "A previous study has shown that vitamin D administration is associated with an increase in adiponectin and a decrease in leptin level in end-stage renal disease patients." (PMID 35684085, 2022). "Previous studies found the relationship between leptin levels and chronic kidney diseases, but we focused on the vulnerable populations, the middle-aged and elderly adults." (PMID 36619557, 2022). "There has been great interest in the role of this hormone in chronic kidney disease-related protein energy wasting; thus, a positive leptin correlation with body mass index and fat mass was confirmed." (PMID 34441040, 2021). "It was also shown that administration of vitamin D led to decline in serum leptin level in end-stage renal disease patients on hemodialysis." (PMID 29295491, 2017). "Serum leptin levels of chronic kidney disease patients have been detected higher than normal population." (PMID 28083046, 2016). "Ghrelin and leptin remained significant predictors of death independently of other potential confounders, such as the presence of metastasis or chronic kidney disease." (PMID 25400234, 2014). "In a multiple Cox regression model, all the variables found to be significantly associated with the endpoint at univariate analysis (ghrelin, obestatin, leptin, metastatic disease and chronic kidney disease) were tested to identify independent predictors." (PMID 25400234, 2014). "The serum leptin concentration is increased in patients with chronic renal failure or undergoing dialysis and the serum leptin increases by 189% within a month after the initiation of PD treatment." (PMID 20454534, 2010).
chronic kidney disease (continued). "It is also described that free leptin may play a role as predictive factor of cardiac function in pediatric patients with chronic kidney disease." (PMID 40152811, 2025). "Leptin potentially exerts atherogenic effects.This study evaluated the relationship between serum leptin levels and aortic stiffness in patients with stage 3–5 chronic kidney disease (CKD)." (PMID 32403968, 2020). "LEP is an energy metabolism hormone that enhances mineralization both in bone and in vascular tissue while GPNMB, is a glycoprotein implicated in end-stage renal disease (ESRD) a pathological condition associated to ectopic calcifications." (PMID 25380738, 2014). "Serum leptin is generally elevated in chronic kidney disease and hemodialysis." (PMID 28197430, 2012). "In addition, patients with end-stage renal disease have higher level of plasma leptin, which was due to the increased leptin production." (PMID 21304902, 2011). "In the chronic kidney disease (CKD) population, including those receiving dialysis, higher levels of leptin have been observed, presumably due to decreased renal degradation and clearance, increased production, and uremic factors." (PMID 41295840, 2025). "A link between increased plasma leptin concentrations and chronic kidney disease (CKD) has been reported, which is possibly due to reduced renal clearance." (PMID 36901837, 2023). "Participants were reclassified into three subgroups according to their leptin levels and the bar chart reveals the prevalence of chronic kidney disease (CKD) in each group." (PMID 36619557, 2022). "A study in chronic kidney disease (CKD) patients with metabolic acidosis revealed that serum leptin was significantly increased by treating patients with a daily low to moderate dose (0.05-0.2g/kg) of sodium bicarbonate." (PMID 22853725, 2012). "In turn, hyperleptinemia may contribute to the development of chronic kidney disease (CKD), which further impairs leptin excretion and exacerbates elevated leptin levels through a harmful positive feedback loop." (PMID 39057043, 2024). "Patients with chronic kidney disease (CKD) had elevated leptin due to reduce plasma clearance." (PMID 34258271, 2021). "Leptin is an adipokine that regulates various metabolism, but its association with secondary hyperparathyroidism (SHPT), a clinical manifestation of chronic kidney disease-mineral and bone disorder (CKD-MBD), remains obscure." (PMID 27307101, 2016). "Elevated leptin levels are present in chronic kidney disease (CKD), independent of body mass index (BMI), age, glucose, and HDL cholesterol concentrations." (PMID 40699654, 2025). "This review explores the potential role of two adipocytokines produced by EAT, adiponectin and leptin, as modulators of CVD in patients affected by chronic kidney disease (CKD)." (PMID 32024124, 2020). "Furthermore, since leptin is elevated in non-dialyzed patients with chronic kidney disease, it is even more tempting to speculate about such a relationship." (PMID 36555328, 2022). "Visceral adipocytes have been shown to produce an array of adipocytokines that could contribute to endothelial injury in the kidney influencing progression to chronic kidney disease (CKD), such as angiotensinogen, TNF-α, plasminogen activator inhibitor-1, resistin, ghrelin, and leptin." (PMID 31152254, 2019).